AKT1 (AKT serine/threonine kinase 1)
Diseases named in the same sentence as AKT1 in open-access papers (continued):
Sharing a sentence is not in itself a finding about the gene and the disease.
ovarian carcinoma (continued). "Furthermore, several clinical trials are currently needed to investigate the efficacy of AKT1 and VEGFA inhibitors in the treatment of ovarian cancer." (PMID 38666020, 2024). "Thus, targeting the AKT1 and VEGFA signaling pathways is a promising approach for treating ovarian cancer." (PMID 38666020, 2024). "Moreover, AKT1 and VEGFA can interact with each other, forming a positive feedback loop that further promotes ovarian cancer progression." (PMID 38666020, 2024). "Additionally, the positive correlation between HK2 and p-Akt1, fibronectin, MMP9 expression in human ovarian cancer samples was verified by using Pearson correlation analysis." (PMID 35953860, 2022). "AKT1 and EGFR play major roles in tumour progression and metastasis in ovarian cancer." (PMID 31895688, 2020). "Following the definition of key regulators, we could able to identify five KRs, namely, AKT1, KRAS, EPCAM, CD44 and MCAM, that are key regulators (organizers) of the ovarian cancer network." (PMID 31752757, 2019). "These high levels of alteration in the PI3K/AKT/PTEN pathway indicate a potential issue for Par-4 activity, because of AKT1 negative regulation, in endometrial and ovarian cancers and are also known for being important key protein related to the chemoresistance of the feminine cancers." (PMID 27175591, 2016). "No change in AKT1 was observed at either the RNA or protein level, indicating that AKT1 is not involved in miR-29b's regulation of the Warburg effect in ovarian cancer cells." (PMID 26512921, 2015). "Finally, we transfected AKT1 into ovarian cancer cells with or without 6RK73 treatment and found that AKT1 overexpression reactivated AKT1/Sp1/c-Myc signaling and reversed 6RK73-induced growth suppression." (PMID 41584043, 2026). "Therefore, we hypothesize that the cytotoxic effects of 6RK73 in ovarian cancer cells may occur through a UCHL1-independent mechanism, potentially involving suppression of the AKT1/Sp1/c-Myc signaling axis." (PMID 41584043, 2026). "Our findings also highlight the therapeutic implications of targeting AKT1 and VEGFA pathways to mitigate cellular proliferation and growth, contributing valuable insights into the chemical constituents of indigenous Saudi plants and their synergistic mechanisms against ovarian cancer." (PMID 38666020, 2024). "Moreover, in order to confirm the positive correlation between the expression of HK2 and p-Akt1, Fibronectin and MMP9 in human ovarian cancer tissues, serial sections of human ovarian cancer tissues (n = 25) were immunostained with antibodies specific for HK2, p-Akt1, fibronectin and MMP9." (PMID 35953860, 2022). "In order to determine whether the Akt1 and p-Akt1 expression could be regulated under HK2 expression in human ovarian cancer cell lines, western blot was used to detected the protein levels of Akt1 and p-Akt1 in HK2- modified human ovarian cancer cells." (PMID 35953860, 2022). "Hence, even though AKT1 is significantly important KR in ovarian cancer network, it never tries to dominate the network organization at different levels of organization." (PMID 31752757, 2019). "Thus, under the experimental conditions chosen, Akt1 rather than SGK1 contributes to the therapy resistance of A2780cis ovary carcinoma cells." (PMID 25015419, 2014).
ovarian carcinoma (continued). "While p−AKT (Ser473) can, to some extent, reflect the general pathway activity, the three AKT isoforms (AKT1, AKT2 and AKT3) are not functionally equivalent in ovarian cancer." (PMID 41458598, 2025). "Although BOTs are not entirely recognized as malignant tumors and are not seen as a necessary process of transformation into ovarian cancer, in this study, we found some biomarkers related to EMTs, such as IL6, AKT1, MAPK3, SRC, TWIST1, and TGFB1." (PMID 33921111, 2021). "Directly targeting p70S6K1 also reduces proliferation and invasion in ovarian cancer cells, though there is no rescue of expression of the CDK-inhibitor p27KIP1 that is seen in targeting p100-α or AKT1." (PMID 23591839, 2013).
colorectal cancer (392 papers, 2008 to 2026). A primary or metastatic malignant neoplasm that affects the colon or rectum. "Under methionine-restricted conditions in HCT116, loss of H3K4me3 (histone methylation marks involving trimethylation at lysines 4) resulted in decreased expression of colorectal cancer (CRC)-associated genes such as AKT1, MYC and MAPK." (PMID 34200820, 2021). "AKT1 was an oncogene in several cancer diseases including osteosarcoma, pancreatic ductal adenocarcinoma, colorectal cancer, and breast cancer.Recently, lncRNAs have been implicated in the miRNA/AKT1 axis modulation in human cancers." (PMID 32811869, 2020). "Non-small cell lung cancer cells with KRAS or EGFR mutations and colorectal carcinoma cells also show the dichotomy of AKT1 during tumor progression and metastasis." (PMID 31752925, 2019). "Recently, a rare activating mutation of AKT1 (E17K) has been reported in breast, ovarian, and colorectal cancers." (PMID 18813315, 2008). "Further analysis was conducted via a metabolite–gene–disease interaction network, which illustrated that some of the genes that were tested were directly linked to colorectal cancer in alignment with the metabolites that were found earlier, such as AKT1 and BCL2." (PMID 37233465, 2023). "In summary, we have shown that rs10138227 AKT1 gene variation in the PI3K/AKT/mTOR pathway may be associated with the risk of colorectal cancer." (PMID 33247671, 2020). "AKT1 may function as an oncogene and AKT3 as a tumor suppressor, and AKT mutations have been detected in human colorectal cancer (AKT2) and lung tumors (AKT1 and AKT3)." (PMID 24338765, 2014). "This decrease in the methylarginine level of AKT1 leads to the inhibition of the AKT/mTOR signaling pathway and a subsequent decrease in colorectal cancer cell proliferation." (PMID 40279519, 2025). "NEDD4L knockdown stabilized PRMT5, resulting in the arginine methylation of AKT1, whereas the overexpression of NEDD4L‐R in NEDD4L‐knockdown colorectal cancer cells promoted PRMT5 degradation to attenuate AKT1 methylarginine levels." (PMID 40279519, 2025). "Consistent with published studies, our study demonstrated that PRMT5 methylates AKT1 at R391 to activate the AKT/mTOR signaling pathway in colorectal cancer cells." (PMID 40279519, 2025). "Colorectal cancer with PIK3CA mutations often accompanies mutations in genes such as KRAS, BRAF, PTEN, AKT1, all of which are components of the PI3K signaling pathway or MAPK signaling pathway." (PMID 39555098, 2024). "MiR-4689 has been reported to effectively inhibit Kirsten rat sarcoma virus (KRAS)-driven epidermal growth factor receptor (EGFR) signaling by directly inhibiting KRAS and AKT1 in colorectal cancer cells." (PMID 37858140, 2023). "In this context, increased activation of AKT1 has been reported in both breast and colorectal cancer, whilst pancreatic cancers frequently have increased expression of AKT2." (PMID 36127435, 2022). "Binding of miRNA-422a to the 3′-untranslated region (UTR) of AKT1 leads to decreased production of AKT1, resulting in reduced tumor growth and proliferation in colorectal cancer cells." (PMID 35269443, 2022). "Description of histotypes and special characteristics of the three human colorectal cancer cell lines in which the inhibition of Akt (Akt1/2) phosphorylation, induced by KA25 and KA39, was investigated." (PMID 33916378, 2021). "miR-149 is a proapoptotic miRNA that affects the expression of the Akt1 and E2F1 gene, which has been shown to promote cell growth and cell cycle progression in IBD-associated colorectal cancer." (PMID 34659590, 2021). "The present study attempts to explore the inhibitory impact of KA25 and KA39 derivatives on Akt1 and Akt2 phosphorylation in three colorectal cancer cell lines (HT-29, LoVo, and SW403) with specific PIK3CA and KRAS statuses." (PMID 33916378, 2021).
colorectal cancer (continued). "A recent study investigating the relationship between RAB11FIP2 expression and colorectal cancer progression demonstrated that the AKT1/PI3K pathway was involved in the RAB11FIP2-mediated expression of the oncogenic Matrix metalloproteinase 7 (MMP7)." (PMID 33614606, 2020). "We evaluated the association between single nucleotide polymorphisms (SNPs) of AKT1 and LMTK3 and the risk of colorectal cancer in a case-control study in Moroccan population." (PMID 33247671, 2020). "In summary, we provided experimental evidence suggesting for the first time a novel role for miR-3135b in the protection of chemotherapy-induced Golgi fragmentation via GOLPH3/AKT1/mTOR axis and protective autophagy in colorectal cancer cells." (PMID 32601379, 2020). "The lncRNA RNCR3 participates in the malignant transformation of colorectal cancer through miR-1301-3p/AKT1 axis interaction." (PMID 32811869, 2020). "Our previous study in colorectal cancer also demonstrated a higher incidence of mutations in PI3K/AKT pathway genes (PIK3CA, PTEN, and AKT1) in the EMAST+/MSI-H tumors than in other subtypes." (PMID 32120855, 2020). "According to the prediction of the network pharmacology molecular target of WCAF for regulating the immunity of colorectal cancer, we chose AKT1 for verification.AKT1 protein expression in tumor tissues was examined by IHC." (PMID 33746736, 2020). "Taken together, based on the results presented, our study showed that Akt1 and especially Akt2 are involved in the regulation of homologous recombination in human colorectal cancer cells." (PMID 31847370, 2019). "It should be noted that other studies reported a pro-metastatic effect of AKT1 in prostate, lung and colorectal cancer denying the dichotomic role of AKT1 in these cancer entities." (PMID 31752925, 2019). "This work is based on knock-down and knock-out strategies—we more specifically characterized the importance of Akt isoforms Akt1 and Akt2 for homologous recombination repair of DSBs in human colorectal cancer cells in vitro." (PMID 31847370, 2019). "Similar to our results, in other cancers such as breast, lung, and colorectal cancers, the important role of Akt1 and 2 isoforms have been shown in the process of cell survival through induction of apoptosis." (PMID 31252679, 2019). "AKT1 (beta-catenin) is a key member in Wnt signaling and adherens junction pathways, and AKT1 is an important kinase in focal adhesion, colorectal cancer, and many other pathways." (PMID 29329594, 2018). "GUCY2C modulates homeostatic processes by opposing AKT1 phosphorylation and downstream signaling in intestine and colorectal cancer." (PMID 22384056, 2012). "The SAM programme typed the following genes to be statistically significant in the compared groups as genes differentiating stage I and II of clinical progression of colorectal cancer: AKT1, STAT3, MCL1, and STAT5B." (PMID 22363883, 2011). "Conversely, Escherichia coli Nissle 1917 (EcN), a probiotic strain, exerts antitumor effects in colorectal cancer by inducing apoptosis through the downregulation of AKT1 and Bcl-xL, as well as the upregulation of PTEN and Bax, thereby inhibiting cancer cell proliferation." (PMID 41602751, 2026). "Notably, suppression of EGFR, SRC, STAT3, and AKT1, which are implicated in both inflammation and carcinogenesis, opens avenues for investigating BRLE in chemoprevention of colitis-associated colorectal cancer." (PMID 41465478, 2025). "Moreover, PRMT5‐mediated methylation of AKT1 at R391 increased cell proliferation to enhance colonization, in turn promoting colorectal cancer liver metastasis." (PMID 40279519, 2025). "RIOK1 also cooperated with AKT1 to activate NF‐κB signaling, driving colorectal cancer progression." (PMID 39865406, 2025).
colorectal cancer (continued). "The analysis of single nucleotide polymorphisms of AKT1 and LMTK3 could lead to more complete and accurate risk estimates for colorectal cancer." (PMID 33247671, 2020). "Thus, in the present study, we aimed to investigate the Akt-dependency of HR more specifically in HCT116 human colorectal cancer cells presenting knockout as well as knockdown phenotypes for the AKT-isoforms AKT1 and AKT2." (PMID 31847370, 2019). "To do this, we used human colorectal carcinoma cells with inactivated AKT1 and AKT2 genes." (PMID 31847370, 2019). "MiR-422a inhibits cell proliferation in colorectal cancer by targeting AKT1 and MAPK1." (PMID 29118671, 2017). "Butyrate was shown to suppress colorectal cancer cell motility by inhibiting HDAC activity and decreasing phosphorylation of Akt1 and ERK1/2, suggesting a similar mechanism is involved in HGF." (PMID 40275488, 2025). "Borussertib, an AKT1 inhibitor, and a MEK inhibitor were used to treat both KRAS-mutant pancreatic and colorectal cancer cells, where the cells displayed anti-tumor activity." (PMID 40564038, 2025). "The decrease in the methylarginine level of AKT1 inhibited the AKT/mTOR signaling pathway, consequently decreasing colorectal cancer cell proliferation and resulting in the suppression of colonization." (PMID 40279519, 2025). "Quercetin and kaempferol have many of the same targets, such as AKT1, AHR, BCL2, NR4A1, etc., and AHR can inhibit the development of colorectal cancer 119-121." (PMID 37497415, 2023). "Therefore, AKT1 may be the key target of quercetin's anti-colorectal cancer effect." (PMID 35795275, 2022). "Some studies have found that Akt1 signaling significantly suppresses the expression of MMP2, MMP9, HIF1α, and VEGF in colorectal carcinoma cells." (PMID 34394377, 2021). "Correlation between EGFR, AKT1, MYC, KRAS and SRC and, colorectal cancers separately or in combination with the other genes are studied and confirmed." (PMID 29511483, 2017). "In colorectal cancer, RREB1 binds to the AKT1 promoter and activates AKT transcription." (PMID 37596700, 2023). "We showed that phospho‐ERK1/2 and phospho‐Akt1/2/3 are not upregulated in colorectal cancer (CRC) tumors compared to matched mucosa, regardless of KRAS mutation status." (PMID 34919787, 2022). "Using molecular docking, a study to find possible applicable curcumin targets for treating colorectal cancer showed that curcumin could stably combine with EGFR, STAT3, and AKT1." (PMID 36297027, 2022). "In addition, knockdown of AKT1 and AKT2 inhibited cell proliferation and colony growth by attenuating cell cycle progression and upregulating the apoptosis of colorectal cancer cells, similar to resveratrol treatment." (PMID 36430164, 2022). "Thus, our data demonstrate that both Akt1 and Akt2 are involved in double strand break repair via the HRR pathway in the HCT116 human colorectal cancer cell line." (PMID 31847370, 2019). "Although functional experiments showed that NEDD4L prevented colorectal cancer liver metastasis through PRMT5 degradation to attenuate the methylation of R391 in AKT1, we did not obtain direct evidence that NEDD4L mediated PRMT5 degradation to attenuate the methylation of R391 in AKT1." (PMID 40279519, 2025). "Thus, these authors demonstrated that the targeting of AKT1 and AKT2 by resveratrol could be a powerful strategy for chemoprevention or treatment for colorectal cancer." (PMID 36430164, 2022). "However, no variant genotypes of other SNPs (AKT1 (rs1130214, rs3730358, rs1000559097, rs2494737), and LMTK3 (rs8108419, rs9989661)) were associated with a risk of colorectal cancer." (PMID 33247671, 2020).
colorectal cancer (continued). "Two colorectal cancer cell lines, DLD-1 and HCT116, and their corresponding isogenic AKT isoforms knockout cell lines were used to show whether AKT1 or AKT2 were activated after exposure to ionizing radiation and their effect on the expression of MRE11 and DNA-PKcs." (PMID 24338765, 2014). "Western blot analysis displayed that CEA expression was not affected by onalespib treatment in any of the assessed colorectal cancer cell lines, while known HSP90-related markers, such as EGFR and AKT1,2,3, displayed alterations." (PMID 35433442, 2022). "In this study, two colorectal cancer cell lines, HCT116 and DLD-1, were used in which the AKT isoforms, AKT1 and AKT2, have been knocked out with no residual protein expression, which enables the analyses of the different AKT isoforms to be more reliable." (PMID 24338765, 2014).